NRP1 (neuropilin 1)
Diseases named in the same sentence as NRP1 in open-access papers (continued):
Sharing a sentence is not in itself a finding about the gene and the disease.
renal carcinoma (12 papers, 2010 to 2026). A carcinoma arising from the epithelium of the renal parenchyma or the renal pelvis. "By contrast, antibodies binding PlGF-2 or VEGFA to block NRP1 significantly reduced proliferation and migration of Caki-I kidney carcinoma cells in vitro, indicating this receptor mediates additional effects." (PMID 42001946, 2026). "NRP1 mRNA expression level showed low cancer specificity across pan-cancers, and was highest in renal cancer among all the cancer subtypes in the TCGA dataset." (PMID 36338984, 2022). "Studies on renal carcinoma cells have shown that NRP1 is involved in dedifferentiation." (PMID 40277760, 2025). "Additionally, both NRP1 and ACE2 express in the kidney and are associated with various renal diseases, including renal carcinoma." (PMID 34698182, 2021). "Caki-1 renal cancer cells were used as positive control for NRP1 staining." (PMID 21747928, 2011). "Interestingly, emerging evidence suggests that the retained expression of angiotensin-converting enzyme 2 (ACE2), transmembrane serine protease 2 (TMPRSS2), and neurolipin 1 (NRP1) on the renal cancer cell could increase tumor immunogenicity and promote a cytolytic effect." (PMID 38255667, 2023). "The newly identified SARS-CoV-2 host factors, NRP1 and ACE2, are significantly upregulated in renal carcinomas." (PMID 34698182, 2021). "This core was composed of several proteins with angiogenic functions in renal cancer including VEGFA, NRP1 and KDR (VEGF receptor-2), the latter of which may have predictive value in ccRCC." (PMID 29861861, 2018). "In addition, the emerging findings investigating the clinical implications of ACE2, TMPRSS2, and NRP1 expression on renal cancer cells for RCC treatment, and the prognostic significance of gene signatures related to SARS-CoV-2 infection in renal cancer cell patients will be reviewed." (PMID 38255667, 2023). "Similar results were found using human kidney carcinoma ACHN cells, which also express NRP1 but not VEGFR-2." (PMID 20087344, 2010).
oral squamous cell carcinoma (11 papers, 2014 to 2023). "High levels of NRP-1 expression significantly correlated with a shorter overall survival in both Oral Squamous Cell Carcinoma and Oropharyngeal Squamous Cell Carcinoma diagnosed patients, suggesting a prognostic role for this protein." (PMID 34359721, 2021). "For instance, lncRNA OIP5-AS1 aggravated oral squamous cell carcinoma progression by sponging miR-338-3p to upregulate NRP1." (PMID 32410883, 2020). "Li and colleague’s study revealed that OIP5-AS1 could promote the progression of oral squamous cell carcinoma by regulating the miR-338-3p/NRP1 axis." (PMID 32178636, 2020). "In oral squamous cell carcinoma, NRP1 promotes EMT by activating NF-κB pathway; conversely inhibiting NF-κB pathway reverses the NRP1-mediated EMT process." (PMID 31547193, 2019).
endothelial dysfunction (10 papers, 2009 to 2026). In vascular diseases, endothelial dysfunction is a systemic pathological state of the endothelium (the inner lining of blood vessels) and can be broadly defined as an imbalance between vasodilating and vasoconstricting substances produced by (or acting on) the endothelium. "Gain- and loss-of-function experiments have confirmed that EP300 transcriptionally activates NRP1, promoting endothelial dysfunction in PAH." (PMID 41402732, 2025). "Together, these findings support a mechanistic model in which EP300 promotes endothelial dysfunction in PAH through epigenetic activation of NRP1." (PMID 41402732, 2025). "Here, we identify EP300 as a key chromatin regulator that promotes endothelial dysfunction in PAH through H3K27ac-dependent activation of NRP1, a coreceptor for VEGFR2 involved in vascular permeability, inflammation, and remodeling." (PMID 41402732, 2025). "Whether NRP1 modifies the risk associated with APOE-ε4 allele by increasing EC permeability or whether compensatory mechanisms upregulate its expression to compensate for the endothelial dysfunction by promoting protective pathways such as the ABCB8/NRP1 pathway it is yet to be established." (PMID 32911833, 2020). "To determine whether NRP1 contributes functionally to endothelial dysfunction in PAH, we assessed its role in promoting proliferative and oxidative phenotypes in PAECs." (PMID 41402732, 2025). "Fourth, while we demonstrate that EP300 regulates NRP1 via H3K27ac, genome-wide chromatin immunoprecipitation studies are needed to map direct EP300 binding sites and to elucidate the broader enhancer landscape underlying endothelial dysfunction in PAH." (PMID 41402732, 2025). "To determine whether NRP1 mediates EP300-induced endothelial dysfunction, we overexpressed EP300 alone or in combination with the NRP1 inhibitor EG00229 in FD-PAECs and assessed endothelial cell proliferation and oxidative stress." (PMID 41402732, 2025). "Furthermore, our finding of NRP1 among the critical proteins supports the role for both inflammation, and endothelial dysfunction in the pathophysiology of AD." (PMID 39877089, 2025). "Notably, co-treatment with EG00229 markedly attenuated both the pro-proliferative and pro-oxidative effects of EP300, implicating NRP1 as a key downstream effector of EP300-induced endothelial dysfunction." (PMID 41402732, 2025). "The MAM domain (IPR000998) in neuropilin 1 (NRP1), representing adhesive function, may be altered to induce endothelial dysfunction in response to stress." (PMID 19320972, 2009). "Circulating miR-1-3p levels predict severity and mortality by enhancing endothelial dysfunction, while miR-142 (targeting TIM-1) and miR-24 (targeting Neuropilin-1) regulate alternative viral entry factors." (PMID 41093073, 2025).
gastric adenocarcinoma (10 papers, 2016 to 2024). "Furthermore, high expression of NRP1 is associated with poor prognosis in most cancer such as adrenocortical carcinoma, gastric adenocarcinoma and CC." (PMID 36406134, 2022). "IL-35 of M2 macrophages was suppressed by NRP1 expression in Stomach Adenocarcinoma (STAD), and the expressed cytokine was served as a major signal in the immune suppression mechanism of STAD." (PMID 34093586, 2021). "Only pancreatic adenocarcinoma (PDAC) and gastric adenocarcinoma (GAC) showed the presence of NRP1 transcripts in endothelial cells in more than 50% of the biopsies." (PMID 30027561, 2018). "NRP1, neuropilin 1, is a membrane-bound coreceptor to the tyrosine kinase receptor VEGF, and thus implicated in the vascularization and progression of different cancers; it has been validated as the miRNA target in stomach adenocarcinoma." (PMID 38672608, 2024). "NRP1 (Neuropilin‐1) is a receptor that is overexpressed in gastric adenocarcinoma." (PMID 38752750, 2024). "In summary, molecules such as DKK1, GHRL, STC1, NRP1 and ITGAV play important roles in the development and prognosis of gastric adenocarcinoma." (PMID 38752750, 2024). "NRP1 expression was upregulated in primary tumor tissue than normal tissue of stomach adenocarcinoma from TCGA data, which was related to tumor stage, and high expression of NRP1 was significantly related to a shorter overall survival." (PMID 34150622, 2021).
osteosarcoma (10 papers, 2015 to 2025). A usually aggressive malignant bone-forming mesenchymal neoplasm, predominantly affecting adolescents and young adults. "In view of the fact that Sema3A is highly expressed in and secreted by cells of osteoblastic origin, and previous findings that implicated Nrp1 and Nrp2 receptors in osteosarcoma, we examined the role of Sema3A in osteolysis and abnormal bone formation associated with osteosarcoma." (PMID 29720701, 2018). "Recent studies have demonstrated that HDAC inhibitors, such as romidepsin, can effectively downregulate neuropilin-1 (NRP1) in osteosarcoma cells, thereby significantly reducing their metastatic potential." (PMID 40332124, 2025). "MG-63 osteosarcoma cells transfected to promote higher NRP1 expression display increased invasion capacity and cell survival after exposure to doxorubicin, whereas NRP1 downregulation in SaOS-2 cells increases chemosensitivity to doxorubicin." (PMID 37894289, 2023). "Previous studies have shown that Sema3A is secreted by osteoblasts, and its co-receptors Nrp1 and 2 have been detected in human osteosarcoma cells." (PMID 29720701, 2018). "Recent studies have reported that osteosarcoma tumours and cell lines overexpress both Nrp1 and Nrp2." (PMID 29720701, 2018). "Previous studies have shown that primary osteoblasts express Sema3A, and osteosarcoma cells express its co-receptor Nrp1 and 229,31,34." (PMID 29720701, 2018). "Since Sema3A is known to selectively bind to its co-receptor Nrp1, further studies were conducted to determine if the anti-migratory effects of osteosarcoma derived Sema3A in our models were truly mediated by Nrp1." (PMID 29720701, 2018). "Neuropilin-1 (NRP-1) is highly expressed in osteosarcoma vascular endothelial cells." (PMID 40904500, 2025). "In osteosarcoma, knockdown of NRP1 can suppress cell invasion and angiogenesis." (PMID 34721048, 2021).
squamous cell carcinoma (10 papers, 2012 to 2025). A carcinoma arising from squamous epithelial cells. "Other studies have implicated Sox2 in regulating NRP1 expression in squamous carcinoma and there is evidence for the regulation of NRP1 in hepatic CSCs by specific microRNAs." (PMID 30678134, 2019). "In contrast to the VEGFR-binding galectin 3, NRP1 directly binds galectin 1, which is overexpressed in tumor-associated capillary ECs in squamous cell carcinoma." (PMID 30717262, 2019). "In xenograft fibrosarcoma and epidermoid carcinoma mouse models, intravenously injected NRP1-specific rhodocetin-αβ selectively destroys the vasculature only in tumors and results in hemorrhage, but not in other tissues." (PMID 30717262, 2019). "In addition, HT1080 fibrosarcoma and A431 epidermoid carcinoma cells likewise expressed both NRP1 and MET especially under chemically induced hypoxia, thus being potential targets of rhodocetin-αβ as well." (PMID 29854288, 2018). "Key words:Semaphorin 3A, neuropilin 1, tongue, squamous cell carcinoma." (PMID 22926477, 2012).
acute myeloid leukemia (9 papers, 2009 to 2023). Acute myeloid leukemia (AML) is a group of neoplasms arising from precursor cells committed to the myeloid cell-line differentiation. "Analyzing NRP-1 protein could be used to predict the shorter overall survival and relapse-free survival rate and related to the complete remission response in acute myeloid leukemia." (PMID 25873749, 2015). "Therefore, NRP-1 may also act as a more aggressive and promising predictor for the poor prognosis of acute myeloid leukemia." (PMID 25873749, 2015).
diabetic nephropathy (9 papers, 2015 to 2024). "One target gene that showed reduced glomerular expression was Nrp1, the gene encoding neuropilin 1, a protein that has been linked to diabetic nephropathy and proteinuria." (PMID 31062503, 2019). "Its role is therefore important in diabetic nephropathy, in which it has been demonstrated that suppression of NRP1 expression may be responsible for podocyte damage and loss, leading to deterioration of renal function." (PMID 35955539, 2022). "Its involvement can be observed in diabetic nephropathy and the presence of NRP1 inhibitor proof-of-concept peptide compounds is of great interest." (PMID 35955539, 2022). "In the glomeruli of diabetic nephropathy mice, the expression of the NRP-1 protein was reduced in podocytes, and the reversals of podocyte injury and proteinuria were associated with the restoration of NRP-1 expression." (PMID 33921219, 2021). "It is speculated that the high expression of NRP1 in the kidney of diabetic patients facilitates the invasion of SARS-CoV-2 into this tissue, while the interaction of both processes leads to depletion of NRP1, which then exacerbates the pathogenesis of diabetic nephropathy." (PMID 35955539, 2022).
liver cancer (9 papers, 2019 to 2025). An epithelial or non-epithelial malignant neoplasm that arises from the liver. "Notwithstanding, when OS and NRP1 association was analyzed within liver cancer studies, different results were obtained after subgroup analysis." (PMID 35884516, 2022). "Here, we assessed the prognostic, diagnostic and clinicopathological value of NRP1 in liver cancer and CRC patients by systematic searches in PubMed, Scopus, Web of Science, Embase and Cochrane Library and a meta-analysis." (PMID 35884516, 2022). "Here, we assessed the prognostic, diagnostic and clinicopathological value of NRP1 in liver cancer and CRC patients." (PMID 35884516, 2022). "In particular, NRP1 methylation, among the tumor-related genes, is found to be associated with survival of colon and liver cancers." (PMID 32408477, 2020). "Moreover, increased levels of NRP-1 are connected with an increased risk of vascular invasion in liver cancer." (PMID 40430075, 2025). "Moreover, high levels of NRP1 were also found to be significantly associated with RFS in liver cancer and PFS in CRC patients." (PMID 35884516, 2022). "The clinical association of NRP1 with OS was analyzed in 11 studies, the only ones that provided survival-associated data, finding that high expression of NRP1 was significantly correlated with a lower survival probability of liver cancer and CRC patients (HR 1.40, 95% CI 1.14–1.71, p < 0.001)." (PMID 35884516, 2022). "NRP1 overexpression was significantly correlated with lower survival in liver cancer patients and with tumor development in hepatocarcinoma patients, and was strongly correlated with an increased risk of vascular invasion in liver cancer and metastasis in CRC and liver tumors." (PMID 35884516, 2022). "Several pieces of research indicated the vital role of NRP1 in liver diseases including liver cirrhosis and liver cancer." (PMID 36653359, 2023). "In summary, this systematic review with meta-analysis summarized and evaluated the potential correlation of high NRP1 expression with worse prognosis and tumor-associated clinicopathological characteristics in CRC and liver cancer patients." (PMID 35884516, 2022). "Overall, these results support the growing interest in NRP1 as a useful diagnostic and prognostic biomarker, as well as its potential as a pharmacological target, in both CRC and primary liver tumors." (PMID 35884516, 2022). "Nevertheless, a significant correlation was observed between high expression of NRP1 and the presence of vascular invasion (invasion, OR 2.48, 95% CI 1.63–3.76, p < 0.001) in liver cancer studies and metastasis (OR 2.19, 95% CI 1.46–3.26, p < 0.001) in both tumor types." (PMID 35884516, 2022). "Thus, authors have carefully suggested that NRP-1 may be an useful marker for liver cancer patient prognosis, as well as for invasive-related characteristics." (PMID 40430075, 2025). "Globally, these results support the potential interest of NRP1 as a prognostic biomarker not only in predicting OS but also in other survival-associated parameters and drug response in patients with advanced CRC or liver cancer, which highlights the interesting role of NRP1 as a therapeutic target." (PMID 35884516, 2022). "The results showed that these genes were highly expressed in liver cancer including CD80, CD44, HAVCR2, NRP1, and LAIR1." (PMID 35067176, 2022). "After statistical analysis, pooled results demonstrated that NRP1 overexpression is correlated with a shorter OS in CRC and liver cancer patients." (PMID 35884516, 2022). "Two studies performed on liver cancer provided data for RFS analysis, which showed a significant correlation of high NRP1 levels with lower RFS (HR 2.21, 95% CI 1.82–2.68, p < 0.001), not finding significant heterogeneity." (PMID 35884516, 2022). "The present study represents the first meta-analysis in which the potential role of NRP1 in CRC and liver cancer prognosis has been evaluated." (PMID 35884516, 2022).
liver cancer (continued). "Despite further studies needing to be accomplished to deeply elucidate the role of NRP1 in invasive-related mechanisms, this protein seems to have a crucial role in modulating invasive processes in different cancer types, including CRC and liver cancer." (PMID 35884516, 2022). "Although a number of investigations showing this potential correlation in other tumor types have been published, no previous study has evaluated the role of NRP1 as a prognostic biomarker in CRC and liver cancer patients through meta-analysis." (PMID 35884516, 2022).
metastatic tumors (9 papers, 2016 to 2025). "Likewise, LRPAP1, MSX1, CCND2, and NRP1 displayed strong associations with monocytes, Tregs and NK cells, especially in metastatic tumors." (PMID 40943183, 2025). "All these genes, except NRP1, had overall upregulated expression in primary tumors and further upregulated expression in metastatic tumors, were all associated with at least two of the following features: poor survival, more aggressive immune subtypes, and higher tumor infiltration." (PMID 32640719, 2020). "HE staining showed that compared with NC-agomir group, miR-378c-agomir alleviated the metastasis and infiltrative growth of metastatic tumors, which was rescued by injecting NRP1 or NORAD-overexpressed cells." (PMID 35164743, 2022). "In some cancer types, the frequency of NRP1 positivity is much higher in metastatic tumor than that in primary tumor." (PMID 27863391, 2016). "Interestingly, among these genes, only NRP1 showed significantly decreased overall expression in cancer tumors and further decreased expression in metastatic tumors." (PMID 32640719, 2020). "Soluble NRP-1 (sNRP-1) can be successfully quantified using ELISA-based approaches and more recently, plasma and tumor tissue levels of NRP-1 were found to be upregulated in node-positive patients with BC and advanced metastatic disease." (PMID 33884469, 2021).
triple-negative breast carcinoma (9 papers, 2017 to 2024). An invasive breast carcinoma which is negative for expression of estrogen receptor (ER), progesterone receptor (PR), and human epidermal growth factor receptor 2 (HER2). "These and other studies support the rationale of the present study, which uses genetic approaches to validate NRP-1 as a potential therapeutic target to suppress the metastatic behavior of triple-negative breast cancer." (PMID 37175499, 2023). "In this report, we show that NRP-1 inactivation in MDA-MB-231 triple-negative breast cancer cells decreased lung metastasis." (PMID 37175499, 2023). "Tumor tissue expression of NRP-1 and PlGF is also upregulated in triple negative breast cancer (TNBC) compared to other subtypes." (PMID 28607365, 2017). "In this study, NRP-1 expression in MDA-MB-231 cells correlated with their ability to produce tumors with metastatic potential in an orthotopic mouse xenograft model of metastatic triple-negative breast cancer." (PMID 37175499, 2023). "For instance, triple negative breast cancer cells expressed high level of Neuropilin-1 (NRP-1)." (PMID 35591858, 2022). "Hence, combining anti-VEGF and anti-VEGFC appears to be relevant for the treatment of triple negative breast cancers for which VEGFC/VEGFR3/NRP1 signaling is detrimental." (PMID 34067671, 2021). "Additionally, the tissue expression of both NRP-1 and PlGF was significantly higher in the tissues of triple negative breast cancer (TNBC) cases compared to the other molecular subtypes." (PMID 28607365, 2017). "Tri-functionalized nanoparticles containing NRP-1 peptides, doxorubicin (DOX) and near-infrared cyanine dye (Cy7) have also been explored in in vitro and in vivo triple-negative breast cancer models." (PMID 37175499, 2023).